CD4 (CD4 molecule)
Diseases named in the same sentence as CD4 in open-access papers (continued):
Sharing a sentence is not in itself a finding about the gene and the disease.
lupus (continued). "We compared in vitro immunoregulatory activity of MDSCs from control or lupus mice and the results showed that MDSCs from lupus mice inhibit CD4+ T cell proliferation weakly (data not shown)." (PMID 33986739, 2021). "In addition, CHIP was upregulated in systemic lupus erythematosus patients’ CD4+ T cells and resulted in the ubiquitination and degradation of regulatory factor X 1 (RFX1), a transcription factor that suppresses systemic lupus erythematosus." (PMID 34831344, 2021). "Double-negative (DN) T cells are defined by the absence of CD4 and CD8 and the ability to produce proinflammatory cytokines like IFN-γ and IL-17 which has been linked to lupus pathogenesis both in human and mice." (PMID 33986739, 2021). "Moreover, urinary mRNA levels of the CXCR3 ligand CXCL10 and CXCR3+ CD4+ T cells in the urine were suggested as non-invasive tools for monitoring the activity in lupus nephritis and might therefore provide a new biomarker for acute nephritis flares in systemic lupus erythematosus patients." (PMID 33598825, 2021). "In addition to CD4+ Th17 cells, IL-17A is produced by γδ T cells, NK cells, and is secreted by CD3+ (CD4-/CD8-) cells infiltrating salivary glands in Sjögrens syndrome and in the plasma from those with systemic lupus erythematosus." (PMID 35003055, 2021). "Nevertheless, the hypomethylation of IFN-related genes in lupus naïve CD4+ T cells did not induce the overexpression of these genes in lupus naïve CD4+ T cells, and it was also not correlated with the disease activity." (PMID 34062726, 2021). "For example, unlike the central role of oxidative stress in lupus pathogenesis, CD4+ T cells of RA patients experienced reductive stress." (PMID 33717180, 2021). "Among the large variety of CD4+ T cell subsets described in the literature, follicular helper T cells (TFH) and regulatory T cells (Tregs) caught a lot of attention from researchers working on lupus." (PMID 34899718, 2021). "The overrepresentation of DMCs in introns has been previously reported in whole blood and neutrophils from systemic lupus erythematosus (SLE) patients, and in CD4+ T cells from SSc patients, while their overrepresentation in intergenic regions has also been found in CD4+ T cells from SSc patients." (PMID 33498390, 2021). "Follicular helper T (Tfh) cells, a CD4+ T cell subset specialized to help germinal center (GC) B cells for high-affinity antibody production, are found in high numbers in patients with SLE and in lupus-prone mice, in correlation with disease activity." (PMID 34156979, 2021). "Moreover, the IFN-γ production efficiency of CD4 and CD8 T cells was negatively correlated to UBA6 levels in patients with lupus." (PMID 35011668, 2021). "They found the global histone H3 and H4 hypoacetylation in active lupus-CD4+ T cells, whereas the global H3K4 methylation was not different between patients and controls." (PMID 33291347, 2020). "CD4+ T cells from SLE patients and lupus-prone mice showed increased mTOR activation." (PMID 32528480, 2020). "MiR-155 is dysregulated in CD4+ T cells from both patients with SLE and lupus-prone mice." (PMID 32308657, 2020). "Compared with those of HCs, the fold enrichment of ac4C peaks showed no distinct difference in the five regions of lupus CD4+ T cells." (PMID 32984334, 2020). "Specifically, NPs better protected lupus mice when concomitantly targeted to CD4+ and CD2+ cells, being the suppressive activity on autoantibody production and disease manifestations superior to the sum of the activities deriving from CD4+ and CD8+ Tregs." (PMID 33391260, 2020). "The autoreactive responses of the CD4+ Th lines were restricted to HLA class II antigens, whereas endogenous heat shock or stress proteins of the HSP60 family that were expressed by the lupus patients’ B cells were involved in stimulating an autoreactive proliferation of the γδ Th cells." (PMID 32085540, 2020).
lupus (continued). "We found that EGR2 mRNA expression levels were significantly upregulated in purified splenic CD4+ T cells from diseased MRL-lpr (14–15 weeks-of-age), B6-lpr (18 weeks-of-age) and B6.sle123 (27–32 weeks of age) lupus mice when compared to their respective controls (MRL and B6 mice)." (PMID 32646370, 2020). "By performing intracellular flow cytometry analysis, we found that EGR2 protein expression was significantly increased in resting lupus (either MRL-lpr or B6.sle123) CD4+ T cells when compared to CD4+ T cells from their respective non-autoimmune controls." (PMID 32646370, 2020). "Furthermore, metformin reduced oxygen consumption, activation and interferon (IFN)-γ production in CD4+ T cells of lupus mice, from healthy controls and SLE patients in vitro, as well as in vivo in lupus mice." (PMID 32825027, 2020). "We have indeed identified significant differences in chromosome X coalescence levels in CD4+ T lymphocytes of inactive and active human female SLE patients compared to healthy (non-lupus) controls, particularly in Tregs (CD4+ CD25+ Foxp3+) and CD4+ CD25− T cell populations." (PMID 31142749, 2019). "In MRL.Faslpr mice, a complete deficiency in IL-10 was accompanied by an enhanced IFNγ production in both CD4+ and CD8+ T cells, and an elevated anti-dsDNA antibody production with more severe clinical diseases, suggesting a protective role of IL-10 in lupus development." (PMID 31546763, 2019). "In IL-23R KO/lpr mice, which do not develop lupus, the total number of DN T cells as well as the total number of IL-17A producing DN T cells and CD4+ T cells was decreased." (PMID 30858513, 2019). "Consistent with our previous findings, CD8+ T cells outnumbered CD4+ T cells in the brain parenchyma by 1.5- to 3-fold, a unique skewing not present in the vasculature or in other organs of lupus-prone mice." (PMID 31356154, 2019). "2DG reduced the number of total splenic CD4+ T cells in all four lupus-prone strains, but not in B6 mice, which is consistent with CD4+ T cells from lupus mice being glycolitic." (PMID 30348969, 2018). "The present study was aimed at characterizing the CD4 T cell populations that are present in the choroid plexus (CP) of MRL/MpJ-faslpr mice, the primary site of brain infiltration in this classic lupus mouse model which exhibits a prominent neurobehavioral phenotype." (PMID 29593732, 2018). "On the contrary, the MRL/lpr mice treated with pCAGGS-Tgfb3 did not exhibit a decrease in the number of CD4+ T cells and B220+ B cells, although B cells and T cells play central roles in the pathogenesis of lupus phenotypes in MRL/lpr mice." (PMID 29963056, 2018). "Although insufficient data have yet been shown regarding how vitamin D affects the lupus CD4+ Th1 cells, the data thus far have shown that the VDR expression in non-lupus CD4+ T cells is not as substantial as other T cell subtypes." (PMID 30103428, 2018). "According to different analyses of CpG methylation, including CD4+ T-cells, CD19+ B-cells, and CD14+ monocytes, done in various immune cell types of several SLE patients, it can be assumed that lupus patients exhibit more global DNA hypomethylation in CD4+ T-cell." (PMID 29803202, 2018). "Therefore, we adopted the B6.MRL/lpr lupus mouse model for this study, since they could mimic the clinical features of SLE patients with respect to NKG2D+CD4+ T cells." (PMID 28455530, 2017). "Critically, we found that in homozygous CD19cre mice, lupus-inducing pristane did not up-regulate thymic CD4-CD8+ but up-regulated CD4+CD8- T cells." (PMID 29163765, 2017). "Murine CD4+CD25-LAG3+ regulatory T cells suppress B cell function through the production of TGF-β3, and it has been reported that TGF-β3 is therapeutic in a mouse model of systemic lupus erythematosus." (PMID 28052118, 2017). "Although the receptor for B7-H4 is not yet identified, CD4+ T cells are crucial since the effect of B7-H4 signal on lupus development is diminished by CD4+ cell deletion." (PMID 29321778, 2017).
lupus (continued). "Subsequent studies used multicolor flow cytometry to demonstrate that these genes are co-overexpressed on the same CD3+CD4+CD28+ T cells, representing a previously unrecognized T cell subset, and that the size of this subset is directly related to lupus flare severity." (PMID 28620656, 2017). "Accordingly, thymic B-cell reduction reduced thymic CD4-CD8+ but not CD4+CD8- T cell numbers in lupus-prone MRL/lpr mice." (PMID 29163765, 2017). "Previous studies have extensively focused on the involvement of CD4+ T cell DNA hypomethylation in lupus since demethylated CD4+ T cells, but not CD8+ T cells, become autoreactive and are able to induce lupus-like disease in mice." (PMID 27070142, 2016). "In lupus-prone MRL/lpr mice, defective DNA methylation and CD70 overexpression in CD4+ T cells could be detected." (PMID 27747498, 2015). "lpr mice develop lymphadenopathy due to accumulation of double negative T cells (DN; TCRαβ+CD4−CD8−B220+), and lupus-like autoimmune disease, probably due to CD4+ T cell hyperactivation." (PMID 25573673, 2015). "Similar to what was observed in the SRBC-immunized BALB/c mice, blocking ICOS signaling led to a significant decrease in number of both GC B cells (∼65% reduction, p<0.01) and Tfh (CD4+ CD44high CXCR5+Bcl6+) cells (∼70% reduction, p<0.01) in this spontaneous autoimmune model of lupus." (PMID 25101629, 2014). "CD4+ regulatory T cells (CD4+ Tregs) were shown to be reduced in the secondary lymphoid organs of the NZB/W F1 lupus-prone mouse model as compared with age-matched nonautoimmune mice." (PMID 24864268, 2014). "When T-cell expression was examined more closely, an increase in Mer expression was found on CD4+ but not CD4- T cells in lupus patients compared with the normal control subjects." (PMID 24650765, 2014). "Additionally, how regulatory CD4+, CD8+, and γδ T cells tune down lupus-related inflammation will be highlighted." (PMID 24864268, 2014). "When CD24hiCD38hi B cells were removed from the culture, higherfrequencies of CD4+IFNγ+ and CD4+TNFα+ T cellswere noted in healthy individuals but not in systemic lupus erythematosus patients; this effect waspartially IL-10 dependent." (PMID 23566714, 2013). "The same mAb injected into NZWB/W lupus-prone mice in another study produced similar results, except that no reduction of CD4+ was demonstrated." (PMID 24000287, 2013). "In the present experiments, we also found that CD4+ T cells from MRL/lpr lupus-prone mice did not release IL-17 even by PMA stimulation though most of them surprisingly expressed IL-17 in the cytoplasm, suggesting T cell abnormality in the mice." (PMID 23585851, 2013). "In humans, CD4+ T cells of patients with SLE were also shown to overexpress CD70 when compared to healthy subjects, although CD70 expression on CD4+ T cells has not been found to be consistently correlated with lupus disease activity." (PMID 24000287, 2013). "In lupus-prone MRL/lpr mice developing a strong lupus disease, a reduced capacity to suppress proliferation and especially, to inhibit interferon-γ (IFN-γ) secretion by syngeneic effector CD4+CD25- T cells occurs in vitro." (PMID 23116248, 2012). "Given the plasticity of the CD4+ T cell subsets, future studies should determine whether the defective regulations of FOXP3+ T cells and Th1/Th17 T cells in lupus patients are functionally related." (PMID 21708033, 2011). "It is of note that the numbers of CD4/CD8 double negative cells or their ratio to CD4/CD25/Foxp3 regulatory T cells are usually taken as a surrogate marker of the autoimmune process in experimental lupus." (PMID 21637713, 2011). "Accordingly, co-injection of TGF-β-primed CD4+CD25+ cells but not control (CD4con) cells significantly prolonged the survival of lupus mice in a manner consistent with a previous report." (PMID 21931768, 2011).
lupus (continued). "While all lupus mice died in 42 weeks following single co-injection of CD4+CD25+ cells treated with TGF-β, more than 60% of lupus mice still survived at this time point after receiving CD4+CD25+ cells treated with both atRA and TGF-β." (PMID 21931768, 2011). "We conclude that, unlike Systemic Lupus Erythematosus, disease status does not alter the ratio of CD4+ to CD8+ T cell subsets in RA." (PMID 20799941, 2010). "We have previously demonstrated that supplementation of endogenous Tregs utilizing a highly purified, exogenously activated and expanded Treg subset characterized by CD4+CD25+CD62LHI expression can inhibit the onset and rate of progression of lupus in (NZBxNZW)F1 (B/W) mice." (PMID 19551149, 2009). "We previously identified an epitope between residues 131–151 present within its RNA recognition motif and targeted early during the progression of the disease by IgG antibodies and CD4+ lymph node cells (LNCs) from H-2k MRL/lpr and H-2d/z (NZBxNZW)F1 lupus-prone mice." (PMID 19390596, 2009). "Interestingly, the proportion of CD45RClow CD4 T cells is strongly increased in AAV patients as compared to healthy controls and patients with systemic lupus erythematosus (SLE)." (PMID 19381293, 2009). "Aside from the changes in NKT cell numbers and the proportions of memory and/or naïve B and CD4+ T cells, first-degree relatives did not generally share the same immune abnormalities as the lupus probands." (PMID 18783591, 2008). "Epitopes recognized by autoreactive CD4+ T cells either in patients or in murine models of lupus or rheumatoid arthritis are not known in the case of the hnRNP-A2 protein." (PMID 17963484, 2007). "For example, in systemic lupus erythematosus (SLE), TBK1 expression in patient immune cells increases with disease activity, particularly in CD4+ T cells and myeloid cells." (PMID 40076567, 2025). "Iron overload promotes pathogenic T-cell differentiation and accelerates disease in lupus-prone models: 1) In MRL/MpJ-Fas (lpr)/J (MRL/lpr) mice, iron overload expands T follicular helper (Tfh) cells, germinal center (GC) B cells, and pro-inflammatory cytokine-secreting CD4 T cells." (PMID 41425591, 2025). "Umbilical cord blood (UCB)-derived CD4+CD25+CD127low regulatory T cells (Tregs) can decrease albuminuria and anti-dsDNA IgG in systemic lupus erythematosus (SLE)." (PMID 39975551, 2025). "In patients with systemic lupus erythematosus (SLE), the levels of m5C and the expression of NSUN2 are reduced in CD4+ T cells." (PMID 39726589, 2024). "Proportions among CD4+ T cells of circulating TFH (cTFH) and cTFH2 cells are increased in several SLE patient cohorts and lupus-like mouse models." (PMID 38649353, 2024). "Similar results were also obtained in the lymph nodes, where S100A9 deletion significantly reversed the activation of macrophages and DCs, reduced the activation of B cells and CD4+ T cells and decreased the percentage of germinal center B cells and plasmacytes in the mLNs of IMQ-induced lupus mice." (PMID 38429401, 2024). "Similar results were also obtained coincidentally in the lymph nodes, where mice that received S100A9−/−-MDSCs showed markedly reduced activation of B cells and CD4+ T cells as well as decreased percentage of germinal center B cells and plasmacytes in the mLNs of IMQ-induced lupus mice." (PMID 38429401, 2024). "As systemic lupus erythematosus (SLE) is a severe autoimmune inflammatory disease and abnormal activation of CD4+ T cells plays predominant roles in the pathogenesis of SLE, we detected the expression of VEGFB and FLT1 in CD4+ T cells from patients with SLE." (PMID 39145452, 2024). "For example, in systemic lupus erythematosus (SLE), estrogen exacerbates the inflammatory response by targeting key immune pathways, including type 1 interferon (IFN) responses, differentiation of CD4+ T helper cells, and survival of self-reactive B cells." (PMID 38843385, 2024).
lupus (continued). "Additionally, IL-2 in combination with TGFβ as well as IL-34 alone have demonstrated the ability to expand both CD4+ Tregs and CD8+ Tregs, which may be leveraged to mitigate diseases such as lupus and GVHD194,195." (PMID 37907738, 2023). "In systemic lupus erythematosus (SLE), nucleic acid self-antigens derived from dying cells are presented to dysregulated T cells, leading to aberrant patterns of differentiation characterized by decreased regulatory T cell production and unchecked CD4+ T cell expansion." (PMID 37766123, 2023). "Firstly, we aimed to compare the yield of detectable SmD1p-specific CD4+ T cells obtained by conventional intracellular staining for the Th1 lineage cytokine IFN-γ, the most abundant pro-inflammatory CD4+ T cell cytokine in murine lupus, with intracellular staining for CD154." (PMID 38022661, 2023). "In lupus-prone mice and SLE patients, GLS2 expression is reduced in CD4+ T cells, and GLS2 reduces ROS levels and promotes the ability of CD4+ T cells to produce IL-2 by demethylating the IL-2 gene." (PMID 36211442, 2022). "In order to observe the influence of oxidative stress on DNA demethylation in the pathogenesis of SLE, we injected H2O2 treated CD4 + T cells into the tail vein of mice to establish a mouse-lupus-like model as in our previous study." (PMID 35001849, 2022). "The BTLA signaling pathway is altered in SLE T cells, and the impaired capacity of BTLA can be corrected by normalizing the lipid metabolism in lupus CD4+ T cells." (PMID 35371016, 2022). "On the other hand, NETosis in systemic lupus erythematosus (SLE), inhibition of TGF-β1 signaling, IL-1 signaling, transcription androgen receptor nuclear signaling, and inhibition of RUNX3 signaling were the main enriched pathways in Th2-enriched CD4+ T cells from peripheral blood in AR patients." (PMID 35246242, 2022). "The autoimmune SmD66-80 T cells in lupus patients are not biased toward IL-17a expression, indicating that these autoimmune CD4+ T cells may not only express IL-17a, but a mixture of other cytokines." (PMID 36389825, 2022). "In CD4+ T cells of patients with lupus, upregulation of EZH2 and H3K27me3 alters the methylation status, and overexpression of EZH2 promotes CD4+ T cells adhesion to endothelial cells through demethylation and upregulation of JAM-A, thus increasing disease activity in lupus." (PMID 35559246, 2022). "Finally, both CD4+ and CD8+ T cells have been shown to infiltrate kidneys of lupus patients." (PMID 35055071, 2022). "We retrieved gene expression omnibus (GEO) dataset GDS4185 which contains FBL mRNA expression data of isolated CD4+ T cells and CD19+ B cells from the blood of Systemic Lupus Erythematosus (SLE) patients and healthy controls." (PMID 35464456, 2022). "Moreover, we did not notice any variation of HVEM expression on CD4+ T cells or Tregs from lupus patients compared to HC." (PMID 34899718, 2021). "Surprisingly, and contrary to what was observed in in vitro stimulated T cells, we noticed that ex vivo CD4+ effector T cells from lupus patients express higher levels of BTLA than those from HC, suggesting that lupus Teffs may be efficiently suppressed in vivo." (PMID 34899718, 2021). "In this study, we set out to investigate the serum IL-35 levels and the surface levels of IL-12Rβ2 and gp130 in CD3+CD4+, CD3+CD4─ and CD3─CD4─ lymphocyte subpopulations in systemic lupus erythematosus (SLE) patients (n=50) versus healthy controls (n=50)." (PMID 34149710, 2021). "Moreover, T cell-targeted nanoparticles loaded with transforming growth factor β (TGF-β) and IL-2 could induce CD4+ and CD8+ Treg cells to inhibit murine lupus." (PMID 34539413, 2021). "Furthermore, an increased percentage of OX40-expressing CD4+ T cells was found in SLE patients, in which it was an indicator of disease activity, and the OX40L-OX40 axis was also found to contribute to lupus pathogenesis by promoting the generation of TFH cells." (PMID 33763492, 2021).